SDC4 (syndecan 4)
Diseases named in the same sentence as SDC4 in open-access papers (continued):
Sharing a sentence is not in itself a finding about the gene and the disease.
neuroblastoma (2 papers, 2021 to 2023). Neuroblastoma (NB) is the most common solid, extracranial childhood tumor. "SH-SY5Y cells, a frequently utilized neuroblastoma cell line, show shallow levels of SDC4 expression." (PMID 36834552, 2023). "Overexpression of SDC4 into the poorly transducible neuroblastoma SH-SY5Y cell line increased AAV9-mediated gene delivery." (PMID 36834552, 2023). "Using microarray dataset analysis, Knelson and collaborators demonstrated that syndecan-4 expression is reduced in neuroblastoma in comparison with benign neuroblastic tumors and is high in the Schwannian stroma." (PMID 33810567, 2021).
preeclampsia (2 papers, 2019 to 2020). Preeclampsia is a hypertensive disorder of pregnancy that is characterized by new-onset hypertension with proteinuria presenting after 20 weeks of gestation, and depending on mild or severe forms may initially present with severe headache, visual disturbances, and hyperreflexia. "A role for syndecan-4 has also been implicated in trophoblast migration and, consequently, the pathogenesis of preeclampsia." (PMID 33178691, 2020). "Both western blot and immunohistochemical analysis showed increased SDC4 in placentas from preeclampsia compared to controls." (PMID 31308409, 2019). "There was a significant increase in SDC4 expression in placentas collected from early-onset preeclampsia (2.5-fold higher expression compared to controls, N = 6, P < 0.0001)." (PMID 31308409, 2019). "Even higher expression of SDC4 was detected in placentas collected from patients with preeclampsia and HELLP syndrome (4.3-fold higher expression than placentas from control pregnancies, N = 4, P < 0.0001)." (PMID 31308409, 2019). "Moreover, we show that SDC4 is dynamically regulated in placenta throughout pregnancy, and that aberrant placental expression of SDC4 is evident in early-onset preeclampsia." (PMID 31308409, 2019). "Interestingly, we observed the opposite effect: placental SDC4 expression was increased in preeclampsia and further increased in placentas of preeclampsia patients with HELLP." (PMID 31308409, 2019). "SDC4 expression was assessed in placentas obtained from normotensive pregnancies, and placentas from pregnancies complicated by severe preeclampsia with and without the preeclampsia variant HELLP (hemolysis, elevated liver enzymes, low platelets)." (PMID 31308409, 2019). "Furthermore, SDC4 expression is induced in low oxygen conditions in human EVTs, and is also increased in placentas from preeclampsia, which may be a consequence of the pathological environment in which the placenta is situated." (PMID 31308409, 2019). "Inflammation is a prominent feature of preeclampsia and HELLP, so it is possible that the inflammatory environment contributes to higher SDC4 expression in preeclamptic placentas." (PMID 31308409, 2019). "Therefore, in future studies, we will assess SDC4 expression in a larger cohort of placental tissues and in maternal plasma collected from normotensive or preeclamptic pregnancies, to determine whether SDC4 expression can be used to improve detection of preeclampsia prior to when symptoms manifest." (PMID 31308409, 2019).
rhabdomyosarcoma (2 papers, 2022 to 2025). A rare aggressive malignant mesenchymal neoplasm arising from skeletal muscle. "Based on our present study on the role of syndecan-4 in myoblast differentiation and considering the unknown role of syndecan-4 in rhabdomyosarcoma, we investigated the presence of syndecan-4 copy-number amplification and loss events in human rhabdomyosarcoma samples." (PMID 35128576, 2022). "Beyond its role in physiological muscle differentiation and fusion, syndecan-4 expression exhibits alterations in human rhabdomyosarcoma samples." (PMID 35128576, 2022). "According to copy-number analysis, syndecan-4 was highly amplified in rhabdomyosarcoma, especially in FNRMSs, as genomic analyses revealed copy-number amplification events in 28% of fusion-negative tumors." (PMID 35128576, 2022). "To summarize, we described the role of syndecan-4 in muscle differentiation and its expression in rhabdomyosarcoma." (PMID 35128576, 2022). "Because the activation of Rac1 GTPase increases myoblast fusion, Rac1 is necessary and sufficient for rhabdomyosarcoma cell migration and invasion, and syndecan-4 regulates Rac1 level, we next analyzed the role of Rac1 in syndecan-4-dependent myoblast differentiation and fusion." (PMID 35128576, 2022). "Therefore, our results provide insight into the molecular etiology of rhabdomyosarcoma and syndecan-4 could be a potential drug target for this aggressive tumor group in the future." (PMID 35128576, 2022). "Due to the unknown role of syndecan-4 in skeletal muscle-derived rhabdomyosarcomas, the rate of syndecan-4 copy-number amplification or gene loss in fusion-positive and fusion-negative rhabdomyosarcomas remains unclear." (PMID 35128576, 2022). "Syndecan-4 copy-number amplification was observed in 28% of human fusion-negative rhabdomyosarcoma tumors and was accompanied by increased syndecan-4 expression based on RNA sequencing data." (PMID 35128576, 2022). "However, the role and expression of syndecan-4 in rhabdomyosarcoma have not been yet examined." (PMID 35128576, 2022).
seminoma (2 papers, 2013 to 2024). A radiosensitive malignant germ cell tumor found in the testis (especially undescended), and extragonadal sites (anterior mediastinum and pineal gland). "The presence of syndecan-4 in the tumour stroma was associated with nodal metastasis, vascular and lymphatic invasion, and disease stage only in seminomas." (PMID 23844358, 2013). "Stromal staining for syndecan-4 was found in seminomas and it was associated with nodal metastasis (P = 0.04), vascular/lymphatic invasion (P = 0.01), and disease stage (P = 0.04)." (PMID 23844358, 2013). "Loss of syndecan-4 overexpression on the surface of tumour cells in NSGCTs is correlated with aggressiveness in contrast to less aggressive seminomas where syndecan-4 is highly expressed constantly." (PMID 23844358, 2013). "Additionally, the loss of syndecan-4 expression in tumor cells in NSGCTs and the higher expression of syndecan-4 in stromal cells in seminomas are associated with metastatic potential in TGCTs." (PMID 38796656, 2024). "In NSGCTs 17/38 patients showed low syndecan-4 expression in contrast to seminoma where 22/23 patients exhibited high syndecan-4 staining." (PMID 23844358, 2013). "Stromal staining in seminomas and reduced levels of syndecan-4 in tumour cells in NSGCTs are related to metastatic potential, whereas stromal staining in TGCTs is associated with neovascularization." (PMID 23844358, 2013). "Less aggressive seminoma cells JKT-1 exhibited higher expression levels of syndecan-4 more than aggressive NSGCT cell lines such as embryonal carcinoma cell line NTERA-2 and teratocarcinoma cell line NCCIT." (PMID 23844358, 2013). "In conclusion, seminomas and NSGCTs are two different categories of testicular tumours with different expression profiles for syndecan-4." (PMID 23844358, 2013). "Stromal syndecan-4 staining was observed in 15/33 (45.5%) patients with seminoma and in 22/38 (57.9%) patients with NSGCTs." (PMID 23844358, 2013). "The lower expression of syndecan-4 in NSGCTs compared to seminomas but still higher than that found in the corresponding normal cells is significantly correlated to the metastatic potential of these tumours." (PMID 23844358, 2013). "Stromal syndecan-4 staining was seen both in stromal cells and in collagen tissue mainly in seminomas of advanced stage, and in NSGCTs independently of disease stage." (PMID 23844358, 2013). "In seminomas, high percentage of tumour cells exhibited membranous and/or cytoplasmic staining for syndecan-4 in all cases." (PMID 23844358, 2013). "Furthermore, stromal expression of syndecan-4 promotes angiogenesis in TGCTs and metastatic potential only in seminomas." (PMID 23844358, 2013). "Both seminomas and NSGCTs have shown stromal staining for syndecan-4." (PMID 23844358, 2013). "Our results indicate that syndecan-4 is differentially expressed in seminomas and NSGCTs and might be a useful marker." (PMID 23844358, 2013). "Statistically significant increase in the expression for syndecan-4 was detected in both NSGCTs (relative fluorescence median ± SE, 0.64 ± 0.11) and seminomas (relative fluorescence median ± SE, 0.79 ± 0.14), suggesting a higher expression of syndecan-4 by tumour cells or activated stromal cells." (PMID 23844358, 2013). "Although increased levels of syndecan-4 in tumour cells may promote cell growth, the imbalanced upregulation of syndecan-4 in seminomas may be related to the lower metastatic potential of these cells, which is a general characteristic of this type of testicular tumours." (PMID 23844358, 2013).
synovitis (2 papers, 2023 to 2024). Inflammation of a synovial membrane. "In our study, we demonstrated that SDC1 and SDC4, as well as molecules that are involved in syndecan regulation (exostosins, sulfotransferases), showed increased expression in OA-related synovitis in comparison with those in the controls." (PMID 38674142, 2024). "Our study demonstrates that SD1 and SDC4, as well as molecules involved in syndecan regulation (exostosins, sulfotransferases), show increased expression in OA-related synovitis compared with those in controls." (PMID 38674142, 2024). "In light of previous reports that identified shed SDC4 in the joint fluid of patients with OA and that SDC4 is associated with OA progression, the possibility that shed SDC4 induces synovitis must also be considered." (PMID 37626753, 2023). "SDC1, SDC4, NDST1 and EXT2 seem to be involved as inflammation moderators in low-grade OA synovitis and, therefore, should be further investigated as potential markers of disease progression and therapeutic goals." (PMID 38674142, 2024). "Still, we concluded that syndecans (SDC1, SDC4), exostosins (EXT2) and sulfotransferases (NDST1) play a role in the progression and control of synovitis and, consequently, are potential therapeutic targets." (PMID 38674142, 2024). "Therefore, our data provide more information in support of syndecan (SDC1, SDC4), exostosin (EXT2) and sulfotransferase (NDST1) involvement in the progression and control of synovitis." (PMID 38674142, 2024). "In an in vivo study, SDC4 inhibited cartilage degeneration without synovitis in an OA mouse model at 6 and 8 weeks." (PMID 37626753, 2023).
type 2 diabetes (2 papers, 2024 to 2025). "We then explored the circulating levels of SDC4 in a cohort of patients with type 2 diabetes (T2D), a prototypical ARD that is linked with the accrual of senescent endothelial cells and exhibits a circulating signature that mirrors many of the hallmarks of aging and senescence." (PMID 39164788, 2024). "Patients with resistant arterial hypertension and type 2 diabetes present higher serum Sdc4 levels." (PMID 40180176, 2025).
abdominal aortic aneurysm (1 paper, 2024). Enlargement and ballooning of the vessel that supplies arterial blood to the abdomen, pelvis and legs. "Furthermore, silencing SDC4 has been shown to enhance abdominal aortic aneurysm formation and VSMC phenotypic switching through the RhoA/G-actin/MRTF-A pathway 32, providing evidence that SDC4 can regulate ROCK function and participate in vascular remodeling." (PMID 39659565, 2024).
aneurysm (1 paper, 2025). Bulging or ballooning in an area of an artery secondary to arterial wall weakening. "It encompasses four components: syndecan-1, syndecan-2, and syndecan-4 (with syndecan-3 only expressed in neural tissue), which have a fundamental role in regulating the events of acute and chronic aorta damage subsequently correlated with the formation of aneurysms." (PMID 39940978, 2025).
atrial fibrillation (1 paper, 2025). A disorder characterized by an electrocardiographic finding of a supraventricular arrhythmia characterized by the replacement of consistent P waves by rapid oscillations or fibrillatory waves that vary in size, shape and timing and are accompanied by an irregular ventricular response. "Increased Sdc4 shedding is observed in patients with atrial fibrillation, which is correlated with atrial oxidative and inflammatory response." (PMID 40180176, 2025).
brain tumor (1 paper, 2023). "Next, we evaluate whether the high expressions of collagen type I receptors (ITGAV, ITGB8, SDC1, SDC4, and CD44) in tumor tissues, i.e., tumor receptors, are related with the prognosis of patients with brain tumor." (PMID 37479733, 2023).
cataract (1 paper, 2017). Partial or complete opacity of the crystalline lens of one or both eyes that decreases visual acuity and eventually results in blindness. "Consistently, immunofluorescent staining showed increased expression of SDC-4 in the LECs of the anterior capsule from age-related cataract patients." (PMID 28703800, 2017). "We found that SDC-4 level in LECs of cataract patients is significantly upregulated, which can subsequently promote cell proliferation and migration." (PMID 28703800, 2017). "Taken together, our data from in vitro human LECs, in vivo mouse ASC model, as well as human cataract patients consistently support the idea that targeting SDC-4 can effectively suppress bFGF-induced proliferation and migration, as well as integrin-mediated adhesion of LECs." (PMID 28703800, 2017).
cerebral amyloid angiopathy (1 paper, 2023). "SRGN and SDC4 were over-expressed in most of the areas, and immunohistochemistry revealed the presence of SRGN in all three types of AD lesion: neuritic plaques, cerebral amyloid angiopathy, and neurofibrillary pre-tangles and tangles." (PMID 37762527, 2023).
Chagas disease (1 paper, 2017). A parasitic infection caused by Trypanosoma cruzi. "In the current study, we provided the first evaluation of syndecan-4 as a biomarker for heart disease severity in a population with Chagas disease." (PMID 29232393, 2017). "The mean concentration of syndecan-4 in subjects with Chagas disease was 15.4 ± 7.7 ng/ml." (PMID 29232393, 2017). "Therefore, additional studies in human heart samples may help clarify whether syndecan-4 expression is increased in the heart tissue in individuals with chronic Chagas cardiomyopathy, as seen in the experimental model of Chagas disease." (PMID 29232393, 2017). "Despite the lack of correlation between syndecan-4 and cardiac disease severity, our analysis in the clinical setting of Chagas disease showed a moderate to strong correlation between LVEF and concentration of NT-ProBNP." (PMID 29232393, 2017). "The concentration of syndecan-4, however, was not different among subjects with different forms of Chagas disease." (PMID 29232393, 2017). "However, the levels of syndecan-4 in subjects with Chagas disease have not so far been investigated." (PMID 29232393, 2017).
coeliac disease (1 paper, 2019). "Heparan sulfate proteoglycans (HSPGs), syndecan-4 (Sdc4) especially, have been suggested as potential partners of transglutaminase-2 (TG2) in kidney and cardiac fibrosis, metastatic cancer, neurodegeneration and coeliac disease." (PMID 30621228, 2019).
COVID-19 (1 paper, 2025). A disease caused by infection with severe acute respiratory syndrome coronavirus 2. "Single-cell sequencing datasets of IPF (GSE213017), COVID-19 (GSE227136 + GSE149878), radiation-induced PF in mice (GSE211713) and BLM-induced PF in mice (GSE210341) revealed high levels of SDC4 mRNA in fibroblast cells." (PMID 40747330, 2025). "The dataset for analyzing the expression level of SDC4 in IPF, COVID-19 related PF, radiation-induced PF and BLM PF is sourced from the GEO database and can be accessed and downloaded from the original studies." (PMID 40747330, 2025).
dementia (1 paper, 2025). Loss of intellectual abilities interfering with an individual's social and occupational functions. "Despite most of these being more prominently dysregulated in AD (e.g., SDC4, ITGB2, MIF, and sTREM1), a small subset of proteins showed an opposite effect between these dementias (e.g., CHL1, GPC1, and CNTN5)." (PMID 40866991, 2025).
diabetic cardiomyopathy (1 paper, 2016). Diabetic cardiomyopathy is a disorder of the heart muscle in people with diabetes. "Membrane proteoglycans Gpc3 and Sdc1 have not yet been demonstrated to play a role in the development of diabetic cardiomyopathy, however, increased expression of the heparan sulfate proteoglycans Gpc1 and Sdc4 has been shown to lead to diastolic dysfunction in streptozotocin-induced diabetic rats." (PMID 27496100, 2016).
diffuse systemic sclerosis (1 paper, 2019). "Moreover, it has been reported that syndecan-4 is overexpressed in the fibroblasts of patients with diffuse systemic sclerosis, and reduces the ability of contract TGF-β-induced collagen matrix and ERK activation in dermal fibroblasts." (PMID 31600983, 2019).
esophageal squamous cell carcinoma (1 paper, 2025). Esophageal squamous cell carcinoma (ESCC) is a type of esophageal carcinoma (EC) that can affect any part of the esophagus, but is usually located in the upper or middle third. "Ligand - receptor pairs midkine - syndecan 4 (MDK - SDC4) and MDK - nucleolin (NCL), which is associated with tumor growth and communication between tumor cells and cancer-associated fibroblasts (CAFs) in esophageal squamous cell carcinoma, were also observed." (PMID 40036264, 2025).
femoral neck fracture (1 paper, 2024). Fractures of the short, constricted portion of the thigh bone between the femur head and the trochanters. "The immunohistochemical expressions of SDC1, SDC2, SDC4, EXT1, EXT2, NDST1 and NDST2 in synovial intima and subintima were then analysed and compared with the control group (patients with femoral neck fracture)." (PMID 38674142, 2024).
head and neck squamous cell carcinoma (1 paper, 2022). A squamous cell carcinoma that arises from any of the following anatomic sites: lip and oral cavity, nasal cavity, paranasal sinuses, pharynx, larynx, and salivary glands. "Accordingly, we subjected head and neck squamous cell carcinoma (HNSCC) and TNBC cells for treatment with SSTNEGFR to probe the involvement of Sdc4 as a partner in EGFR signaling in these cancers." (PMID 35569509, 2022).
idiopathic interstitial pneumonia (1 paper, 2017). A class of diffuse lung diseases that typically affect the pulmonary interstitium, although some also have a component affecting the airways (for instance, Cryptogenic organizing pneumonitis). "Clinical characteristics of idiopathic interstitial pneumonia patients with high and low baseline serum syndecan-4 levels." (PMID 28467516, 2017). "The goal of this study was to clarify the role of syndecan-4 in acute exacerbation of idiopathic interstitial pneumonia." (PMID 28467516, 2017). "Serum syndecan-4 levels were significantly lower in patients with acute exacerbation of idiopathic interstitial pneumonia than in patients in the clinically stable phase." (PMID 28467516, 2017). "Baseline serum syndecan-4 is a possible prognostic biomarker after the onset of acute exacerbation of idiopathic interstitial pneumonia." (PMID 28467516, 2017). "Prognosis was significantly worse in patients with idiopathic interstitial pneumonia with high baseline serum syndecan-4 levels than with low baseline levels." (PMID 28467516, 2017). "The aim of the present study was to clarify the role of syndecan-4 in AE of idiopathic interstitial pneumonia (IIP)." (PMID 28467516, 2017).
interstitial cystitis (1 paper, 2025). A rare chronic debilitating urogenital disease characterized by urinary frequency, urgency, and pelvic pain. "We found that heparanase 1 (HPSE) and syndecan-1 (SDC-1), syndecan-2 (SDC-2) and syndecan-4 (SDC-4) within the SDC family were up-regulated in the interstitial cystitis/bladder pain syndrome (IC/BPS) tissues." (PMID 40408331, 2025).